TTTY4B (testis expressed transcript, Y-linked 4B)
Synonyms: LINC00124; NCRNA00124
Gene: Long non-coding RNA gene on chromosome Y (24,570,202 to 24,607,025, forward strand). Ensembl gene ENSG00000235412.
Homologues: Paralogues in human: TTTY4 (100% identical), TTTY4C (100% identical).